PVR (PVR cell adhesion molecule)
Diseases named in the same sentence as PVR in open-access papers (continued):
Sharing a sentence is not in itself a finding about the gene and the disease.
tumor (continued). "Overall, we delineated cell–cell interaction landscape of tumor cells and immune cells and revealed that Plac1+ tumor cells recruited CD4+ T cells through the CXCL11/CXCR3 axis and then induced Treg differentiation through PVR/TIGIT to shape the immunosuppressive TME of HNSCC." (PMID 40056047, 2025). "The poliovirus receptor (PVR or CD155), a member of the adhesion molecule family, serves as a ligand for TIGIT and is highly expressed on the surface of various tumor cells, inhibiting the activation of T and NK cells, thus promoting tumor metastasis and progression." (PMID 38291470, 2024). "Moreover, tumor cells isolated from patients at the onset of the disease expressed PVR, whereas patients experiencing disease relapse lacked expression of PVR, indicating a possible link between PVR expression and disease progression." (PMID 39294470, 2024). "Because PVR and NECTIN2 can both act on TIGIT, compared to the currently popular PDL1/PDLD1 blockers, TIGIT may not only reverse the exhaustion state of CD8 T cells but may also improve the tumor immunosuppressive microenvironment to a certain extent." (PMID 36685571, 2022). "Interestingly, the PVR/CD155 expression on the surface of 4T1 cells was down-regulated after the cells were infected with VV, while its expression on the other three tumor cells did not change significantly." (PMID 33581644, 2021). "With relatively small molecular weight, PVR mutants without Fc segment might be utilized as protein drugs for cancer treatment, which needs further researches to test the anti-tumor effects of the mutant proteins both in vitro and in vivo." (PMID 33557880, 2021). "In this study, we demonstrated that azelnidipine could dual target SIRPα and PVR, simultaneously block the negative signal pathway, enhance the phagocytosis of tumor cells by macrophages, and significantly inhibit tumor growth." (PMID 34068552, 2021). "IHC shows that PVR is expressed by tumor cells, but not by stromal cells in both NE SCLC subtypes." (PMID 32506804, 2020). "First, the TIGIT interaction with PVR is of a much higher affinity compared to the TIGIT interaction with CD112, participating in the negative regulation of activated T cells and NK cells by up-regulating IL-10 expression and down-regulating IL-12 expression in tumor cells or APCs." (PMID 29735917, 2018). "Moreover, IFN-γ production by CD8+ T cells of tumor-draining lymph node and spleen increased along with the inhibition of tumor growth caused by TIGIT blockade with α-TIGIT but not by PVR protein." (PMID 30555485, 2018). "Therefore, we propose that tumor intrinsic TIGIT may deliver inhibitory signals to CD8+ T cells and NK cells by engaging with PVR." (PMID 30555485, 2018). "In addition to the pivotal role played by adhesion molecules (i.e., LFA-1 and CD2) in the NK cell interaction with target cells, engagement of DNAM1, a co-stimulatory receptor specific for Nectin-2 (CD112) and PVR (CD155), contributes to the response against tumor and virus-infected cells." (PMID 28261220, 2017). "However, the role of PVR in tumor progression, as well as its expression in normal cells, should not be underestimated." (PMID 24575100, 2014). "It is worth noting that PVR, NECTIN2 have a low correlation with immune checkpoint receptors in tumors, which may be due to the almost non-existent expression of PVR and NECTIN2 on immune cells and explain the beneficial role of low expression of PVR, NECTIN2 in tumor survival assays." (PMID 39120585, 2024). "Moreover, acetate, as a regulator for immune checkpoint ligand PVR/CD155 driven by PI3K/AKT signaling, can enhance functional responses of CD8+ T cells in TIME and promote the production of IFN-γ, which is expected to become a related drug to promote tumor immunity." (PMID 37122756, 2023).
tumor (continued). "In contrast, PVR and TIGIT did not exhibit close proximity in lepidic tumor tissue but co-localized spatially in solid tissue." (PMID 39474422, 2024). "The binding of PVRL2 to TIGIT is much weaker than that of PVR to TIGIT, suggesting that it does not play a significant role in the tumor immune system." (PMID 39156900, 2024). "Two ligands for TIGIT, CD155 (PVR) and CD112 (PVRL2, nectin-2), are expressed on APCs, T lymphocytes, and on non-hematopoietic cell types including tumor cells." (PMID 39273326, 2024). "TIGIT can bind to the receptors CD155 (poliovirus receptor-PVR), CD112 (PVRL2, nectin-2), and CD113 (Nectin-3) in immune cells, non-immune cells, and tumor cells, resulting in T cell activation and suppression of cytotoxicity." (PMID 34631507, 2021). "TIGIT competes with the immunoactivator receptor CD226 (DNAM-1) for the same ligands: CD155 (poliovirus receptor, PVR) and CD112 (Nectin-2 or PVRL2), expressed on APCs, T cells and some non-hematopoietic cell types like tumor cells." (PMID 34335585, 2021). "Since the elimination of PVR or PVRL2 in NB cell lines was not sufficient to generate a higher cytotoxic activity of NK-92 cells in vitro, we presume that a modification of the tumour cells alone cannot sufficiently improve the lysis." (PMID 40317320, 2025). "Administration of anti-PD-L1 antibodies to isolated, tumour antigen-experienced CCR7+ BMDC in vitro did not alter their phenotype, but the addition of recombinant IFNγ upregulated expression of OX40L, PVR and CD40, consistent with the activated Ccr7_DC.2 state." (PMID 38267413, 2024). "TIGIT inhibitory function is mediated by binding to its ligand the poliovirus receptor (PVR, CD155), and poliovirus receptor-relate 2/Nectin-2 (PVRL2, CD112) which are present on the surface of APCs and non-hematopoietic cells including tumor cells." (PMID 32714317, 2020). "PVR and Nectin-2 are over-expressed in tumors of different histotype and their interaction with DNAM-1 is non-redundant and crucial to obtain an efficient tumor cell killing." (PMID 28456791, 2017). "Whereas PVR:HER2-scFv did not mediate cytotoxic effects, both B7-H6:HER2-scFv and AICL:HER2-scFv promoted NK cell cytotoxicity and induced killing of HER2-positive tumor cells." (PMID 26392331, 2015). "Furthermore, chronic tumor exposure had a negative impact on general NK-cell anti-tumor function, resulting in reduced degranulation and decreased expression of effector cytokines IFNγ and TNFα in NK cells exposed to tumors and re-challenged with either PVR+ and PVR− K562 cells." (PMID 37345049, 2023).
cancer (255 papers, 2004 to 2026). A tumor composed of atypical neoplastic, often pleomorphic cells that invade other tissues. "PVR secreted by Brain metastasis cancer-associated fibroblasts has been shown to enhance the invasive potential of cancer cells." (PMID 39156900, 2024). "To specifically probe the effect of pRb and E2F1 on PVR protein expression, we first transduced cancer cells with a recombinant adenovirus encoding E2F1 (Ad.E2F1)." (PMID 37230983, 2023). "There is an increasing interest in the prognostic effects of PVR expression in patients with cancer, as an elevated PVR expression is associated with poor survival in most cancer types." (PMID 35625835, 2022). "Thus, our results revealed functional mechanisms of KIR2DL5-mediated NK cell immune evasion, demonstrated blockade of the KIR2DL5/PVR axis as a therapy for human cancers, and provided an underlying mechanism for the clinical failure of anti-TIGIT therapies." (PMID 36377656, 2022). "PVR has been shown to be overexpressed in many cancers and is associated with poor prognosis." (PMID 34209558, 2021). "Thus, high expression of PVR is associated with a worse outcome for several types of cancer." (PMID 33343635, 2020). "scRNA-seq analysis revealed enhanced PVR-TIGIT interactions between cancer and immune cells in NOTCH3-high tumors." (PMID 41808828, 2026). "TIGIT is expressed on cytotoxic and helper T cells, Tregs cells, and NK cells, while its main ligand CD155 (PVR) is expressed on MDSCs and cancer cells." (PMID 40003864, 2025). "Results indicated a significant positive correlation between SLC2A1 and immunostimulants across most cancer types, with CD276 and PVR predominantly implicated in LUAD." (PMID 40824962, 2025). "ferroptosis-associated cancer-associated fibroblasts (FerroCAFs) show high expression of the surface marker CD155 (PVR; poliovirus receptor) and of Hmox1, and their intracellular ferrous iron (Fe2+) content is markedly higher than in other CAFs subgroups." (PMID 41514658, 2025). "TIGIT binds primarily to the CD155 receptor, also known as the polio virus receptor (PVR), which is expressed on monocytes, dendritic cells (DCs), fibroblasts, endothelial cells, and tumor cells from many cancers." (PMID 40075753, 2025). "As PVR is differentially regulated in a broad spectrum of cancers, overexpression of PVR has been reported in several malignancies, suggesting its possible use as a prognostic biomarker." (PMID 40369504, 2025). "LEC-derived immune-inhibitory ligands dampen effector T cell function in cancer, neuroinflammation, and infection, and we confirmed the expression of 2 exemplar molecular candidates, PVR and LGALS9, at both the transcript and protein level." (PMID 40663403, 2025). "Among these lC, the poliovirus receptor/poliovirus receptor-like 2 protein (PVR/PVRL2)-TIGIT axis was discovered as potential target for various cancers." (PMID 40317320, 2025). "Provision of IL-15 within the TME likely involves CCR7+ DCs, which express high levels of IL-15 and IL-15RA, co-localize with NK cells in human cancers and can support further molecular interactions such as PVR:TIGIT55,71,72." (PMID 38267402, 2024). "This article comprehensively reviews the immunomodulatory mechanisms centered on PVRL2 and PVR, elucidating their implications for various cancer types." (PMID 39156900, 2024). "PVR is overexpressed in many cancers compared to normal tissue and has been shown to correlate with poor prognosis." (PMID 39156900, 2024). "Younger patient tumors were only enriched for 3 (5%) of these genes including one cancer testis antigen gene (SSX2) and two genes involved in T-cell recognition and killing of cancer cells (PVR, CXCR2)." (PMID 38975340, 2024). "PVR, a glycosylated transmembrane protein involved in cell proliferation, adhesion and motility/metastasis, is upregulated in many cancers." (PMID 37230983, 2023).
cancer (continued). "Consistently, PVR overexpression is correlated with tumor progression and unfavorable prognosis in different cancer cell types." (PMID 36768145, 2023). "High expression of PVR and Nectin2 has been demonstrated on the surface of different solid and hematological human cancers, which become more sensitive to NK cell-mediated killing in vitro and in vivo." (PMID 37760586, 2023). "CD226, TIGIT, and CD96 share the same ligand CD155 (also known as PVR/NECL5/TAGE4), a member of the nectin-like family of adhesion molecules and highly expressed on cancer cells." (PMID 37056782, 2023). "MSCs induce significant upregulation of MHC class I chain-related protein A (MICA) and poliovirus receptor (PVR) levels on these cancer cells." (PMID 36768145, 2023). "PVR/CD155 regulators are overexpressed in malignant tumors and bind to a T-cell immunoreceptor with Ig and ITIM domains to mediate immune escape." (PMID 37122756, 2023). "We next performed multiplex IHC to assess coexpression of TIGIT + on CD8 + T cells and PVR + on CK19 + cancer cells at the protein level." (PMID 36781852, 2023). "The function of PVR in the angiogenesis process for malignant tumors has gradually attracted much attention." (PMID 36552960, 2022). "PVR and related pathway members are highlighted as key regulators of T cell function and response to cancer immunotherapy." (PMID 36552960, 2022). "The results from the TIMER database also demonstrated that the PVR expression was higher in most malignant tumors." (PMID 36552960, 2022). "T cell immunoreceptor with Ig and ITIM domains (TIGIT) interacts with poliovirus receptor (PVR) to contribute to cancer immune escape." (PMID 36544779, 2022). "DNAM-1 is an activating receptor that upon ligation with PVR and Nectin-2, triggers NK cell-mediated cytotoxicity against various cancer cells." (PMID 36419901, 2022). "In this study, we found that PVR was overexpressed in HCC tissues and negatively correlated with prognosis, supporting the potential of PVR as a biomarker to assess cancer progression and prognosis." (PMID 36552960, 2022). "Immunotherapies targeting the TIGIT/PVR axis are now being actively explored in clinical trials in various cancer patients." (PMID 36377656, 2022). "Our findings set the cellular and molecular basis for the inhibitory function of KIR2DL5 and demonstrate the therapeutic potential of blocking the KIR2DL5/PVR pathway in NK cell–based cancer immunotherapy." (PMID 36377656, 2022). "To further explore the KIR2DL5/PVR pathway in various human cancers, we first tried immunohistochemistry (IHC) staining for KIR2DL5, but none of the antibodies worked." (PMID 36377656, 2022). "The poliovirus receptor (PVR) is a member of the immunoglobulin superfamily (Ig SF) and is essential for the promotion of cancer cell proliferation and invasion." (PMID 36552960, 2022). "Studies show that immune checkpoints TDO2, PDCD1, LGALS9, and PVR play an important role in cancer treatment and prognosis." (PMID 36686663, 2022). "Preclinical studies have demonstrated that the TIGIT/PVR axis is an attractive cancer immunotherapy target owing to its roles in modulating CD8+ T cell and NK cell responses." (PMID 36377656, 2022). "Blockade of KIR2DL5 with our new blocking mAb significantly enhanced NK-mediated antitumor immunity both in vitro and in vivo, demonstrating blockade of the KIR2DL5/PVR pathway as an immunotherapy for treating human cancers." (PMID 36377656, 2022). "Using virtual screening in combination with comprehensive methods, we redefined the function of the small molecule compound liothyronine in blocking the interaction between TIGIT and PVR for cancer immunotherapy." (PMID 34068552, 2021). "Remarkably, CD155/PVR on cancer cells interacted with CD226 expressed in CD8+ T cells in all 4 treatment groups, suggesting that this interaction plays a key role in immune modulation." (PMID 34417435, 2021).
cancer (continued). "To further investigate the prognostic potential of PVR, we used TCGA RNA-seq and clinical data to analyze the prognosis across 33 TCGA cancer types." (PMID 34150627, 2021). "Along with its co-inhibitory receptor CD96 (TACTILE), TIGIT can bind to ligand CD155, also known as the poliovirus receptor (PVR), which is upregulated in many cancers." (PMID 33946954, 2021). "Antibodies targeting TIGIT/PVR pathway have achieved good clinical results in cancer treatment, as so far six TIGIT-targeting antibodies were under pre-clinical or clinical trials." (PMID 33557880, 2021). "Overexpression of PVR on cancer cells can restrain T cell and NK cell responses because PVR can negatively manipulate TIGIT functions." (PMID 33557880, 2021). "CD48, CD200 and VISTA are also downregulated in cancer samples, while CD276, LGALS9 and PVR are upregulated in cancer tissue." (PMID 33806327, 2021). "Recent studies have indicated that PVR is related to cell adhesion and migration, adaptive immunity, and cancer." (PMID 33902006, 2021). "Increasing attention has been paid to PVR in cancer immunotherapy since the verification of its role as the shared ligand for the immune checkpoint TIGIT and CD96." (PMID 34068552, 2021). "A small molecule liothyronine was discovered to serve as a potential candidate for cancer immunotherapy by blocking the immune checkpoint TIGIT/PVR." (PMID 32894141, 2020). "The activation of this enhancer is accompanied by PVR expressed in many cancers, such as ESCA, HNSC, and LUSC." (PMID 33343635, 2020). "Our findings identify BMSCs as regulators of NK cell anti-MM response and contribute to define novel molecular pathways involved in the regulation of PVR expression in cancer cells." (PMID 32069911, 2020). "The expression of PVR in tumors were analyzed by using TCGA, Oncomine and GEO database, and in cancer cell lines examined by flow cytometry." (PMID 32894141, 2020). "In NK cells, TIGIT competes with the DNAM-1 (CD226) activating receptor for their common ligands CD112 (PVRL2) and CD155 (PVR) expressed on many cancer cells." (PMID 29023417, 2017). "Among these proteins are many SLC proteins and other transmembrane glycoproteins like Claudine 12, GPR56 or PVR and related proteins which were described as expressed by cancer cell lines." (PMID 25469109, 2014). "However, CD155 (or PVR) and its related PVR/nectin family members, which are expressed on NK cells, play a vital role in the early stages of cancer elimination and in preventing metastasis." (PMID 39847233, 2025). "Our results demonstrate that similar to other cancer entities, the PVR/PVRL2-TIGIT checkpoint axis could serve as a new immunotherapeutic target for NB." (PMID 40317320, 2025). "While no strongly regulated markers emerged, altered surface proteins, including PVR overexpression, may collectively contribute to immune dysregulation, consistent with PVR’s role as a prognostic marker in other cancers." (PMID 39860532, 2025). "Strong and consistent positive correlations were witnessed between ADM and several immune checkpoint genes, including CD274 (PD-L1), CD276, TNFRSF18, TNFSF9, and PVR in pan-cancer analysis, indicating its role in the development of suppressive immune microenvironment and T cell exhaustion." (PMID 40529377, 2025). "Furthermore, the regulatory network of MHC-II+ cancer cells revealed interactions between PVR and coinhibitory receptors including TIGIT and CD96, which induce CD8+ T-cell exhaustion and Treg activation, and subsequently facilitate immune evasion." (PMID 41281745, 2025). "Mechanistically, we observed increased PVR expression in VPS25high cancer cells, and knockdown of VPS25 reduced PVR expression, suggesting that VPS25 may mediate immune evasion through the PVR-TIGIT axis." (PMID 40149859, 2025).